SEMA3A (semaphorin 3A)
Diseases named in the same sentence as SEMA3A in open-access papers (continued):
Sharing a sentence is not in itself a finding about the gene and the disease.
kidney disease (3 papers, 2014 to 2023). "In contrast, excess SEMA3A causes the progression of a variety of kidney diseases, including DN, AKI and CKD, through an increase in albuminuria, kidney fibrosis, apoptosis and inflammation." (PMID 37835781, 2023). "Semaphorin3A (SEMA3A), expressed in podocytes and tubular cells in the mammalian adult kidneys, has been reported to regulate diverse biological functions and be associated with renal diseases." (PMID 32521824, 2020). "Animal studies show that netrin-1 plays a protective role in epithelial cells whereas sema3A may have a pathogenic role in kidney disease." (PMID 25289643, 2014). "On the basis of these studies, SEMA3A plays an important role in kidney morphogenesis and kidney diseases." (PMID 37835781, 2023). "In addition, the detailed mechanisms of SEMA3A underlying kidney diseases are not fully understood;, there are several possible signaling pathways, involving SEMA3A signaling, such as Rac1/NF-κB p65, JNK and TLR4 signaling, which may regulate inflammation and cell apoptosis." (PMID 37835781, 2023). "We have summarized the current knowledge regarding the role of SEMA3A in kidney pathophysiology and its potential use in kidney diseases." (PMID 37835781, 2023). "In this review article, we summarized the current knowledge regarding the role of SEMA3A in kidney pathophysiology and their potential use in kidney diseases." (PMID 37835781, 2023). "Indeed, SEMA3A-mutant mice or the pharmacological-based inhibition of SEMA3A protected from these kidney diseases, suggesting the potential of SEMA3A inhibitory treatment in clinic use in the future." (PMID 37835781, 2023). "In addition, recent accumulated evidence has also revealed important roles of SEMA3A in kidney diseases." (PMID 37835781, 2023). "Taken together, SEMA3A not only regulates kidney development, but also may be involved in kidney diseases." (PMID 37835781, 2023). "SEMA3A has been reported to play important roles in multiple aspects of renal diseases." (PMID 32521824, 2020). "Accumulating evidence has indicated the role of SEMA3A in renal diseases." (PMID 32521824, 2020). "In addition, several reports have demonstrated that the inhibition of SEMA3A ameliorated kidney injury via a reduction in cell apoptosis, fibrosis and inflammation; thus, SEMA3A may be a potential therapeutic target for kidney diseases." (PMID 37835781, 2023). "Therefore, SEMA3A-targeting therapy may be a novel therapeutic option for treatment against a variety of kidney diseases, including AKI, CKD and proteinuric diseases." (PMID 37835781, 2023). "It has been reported that excess SEMA3A expression may accelerate kidney injury in a variety of kidney diseases via the JNK or Akt signaling pathway, suggesting that targeting SEMA3A signaling may be a potential therapy against kidney injury." (PMID 37835781, 2023).
neurological disease (3 papers, 2019 to 2025). "SEMA3A, an axonal guidance molecule that impairs regeneration, has been implicated in the pathogenesis of neurodegeneration in multiple neurological diseases." (PMID 40943667, 2025). "Last, some of the NSPs regulated via Sema3A-p-eIF2α signaling are neurological disease-associated, suggesting links between defective axonal translational control in neural wiring and disease." (PMID 30595434, 2019). "The overexpressed genes are related to glutamate neurotransmitter release cycle, antigen activation of B-cell receptor and Collapsin Response Mediator Proteins (CRMPs) in Sema3A signaling that modulate the immune system in neurological disorders with inflammatory components." (PMID 32438758, 2020).
immune disorders (2 papers, 2022). "Semaphorin 3A (Sema3A), a member of the semaphorin family, is reported to be involved in various immune disorders." (PMID 35798870, 2022).
neurodegenerative disease (2 papers, 2018 to 2023). A disorder of the central nervous system characterized by gradual and progressive loss of neural tissue and neurologic function. "Among Sema3 family members, Sema3A has been reported to play a role in neurodegenerative diseases." (PMID 37316917, 2023).
cardiovascular disease (1 paper, 2023). "Among them, SEMA3A is known as a direct regulator of the SNS innervation in the heart and is associated with cardiovascular disease." (PMID 37291626, 2023). "Given that supplementation of SEMA3A improves cardiac autonomic disorders after MI in rodents, SEMA3A may be a potential therapeutic target of cardiovascular diseases in human." (PMID 37291626, 2023).
central nervous system diseases (1 paper, 2020). "Uncontrolled inflammation and an increase in axonal inhibitory factors such as semaphorin 3A (SEMA3A) impede nerve regeneration in central nervous system diseases." (PMID 32555658, 2020).
heart disease (1 paper, 2023). "In conclusion, Sema3A is a key pathogenic mediator that impairs the angiogenic potential of MiVECs, which leads to cardiac microvascular rarefaction in pressure overload‐induced heart disease." (PMID 37310417, 2023).
musculoskeletal diseases (1 paper, 2022). "Further clinical studies will be needed to investigate fully the therapeutic role of Sema3A on the therapy of musculoskeletal diseases." (PMID 35250478, 2022). "Finally, clinical data showed that Sema3A is significantly correlated with age and BMD, and thus could serve as an early signal for musculoskeletal diseases." (PMID 35250478, 2022).
peripheral neuropathy (1 paper, 2020). A disorder affecting the peripheral nervous system. "We made an interesting observation that the peripheral neuropathy caused by HFD was strongly associated with the decrease in the expression of Sema3a, Neuropilin 1, Plexin A, and A2AR in the spinal cord." (PMID 32566683, 2020).
SEMA3A also shares sentences with these, for which no sentence is quoted: CHARGE syndrome (4 papers); acute leukemia (3); alcohol dependence (3); cryptorchidism (3); psychiatric disorder (3); Brugada syndrome (2); epilepsy (2); genetic disorder (2); hypopituitarism (2); kidney (2); Micropenis (2); Parkinson disease (2); Sinus bradycardia (2); steatosis (2); temporal lobe epilepsy (2); allergic rhinitis (1); Allergy (1); ankylosing spondylitis (1); Anosmia (1); atrial fibrillation (1); benign tumours (1); Cantú syndrome (1); Carcinoma in situ (1); cardiac arrhythmias (1); cellulitis (1); cerebral infarction (1); chronic kidney disease (1); Chronic Lymphocytic Leukemia (1); chronic pancreatitis (1); congenital hypogonadotropic hypogonadism (1).
A further 58 diseases each share a sentence with SEMA3A in 1 paper.